MMS19 (MMS19 cytosolic iron-sulfur assembly component)
Description:
Key component of the cytosolic iron-sulfur protein assembly (CIA) complex, a multiprotein complex that mediates the incorporation of iron-sulfur cluster into apoproteins specifically involved in DNA metabolism and genomic integrity. In the CIA complex, MMS19 acts as an adapter between early-acting CIA components and a subset of cellular target iron-sulfur proteins such as ERCC2/XPD, FANCJ and RTEL1, thereby playing a key role in nucleotide excision repair (NER), homologous recombination-mediated double-strand break DNA repair, DNA replication and RNA polymerase II (POL II) transcription. As part of the mitotic spindle-associated MMXD complex, plays a role in chromosome segregation, probably by facilitating iron-sulfur (Fe-S) cluster assembly into ERCC2/XPD. Together with CIAO2, facilitates the transfer of Fe-S clusters to the motor protein KIF4A, which ensures proper localization of KIF4A to mitotic machinery components to promote the progression of mitosis. Indirectly acts as a transcriptional coactivator of estrogen receptor (ER), via its role in iron-sulfur insertion into some component of the TFIIH-machinery.
Synonyms: hMMS19; MMS19L; MET18; CIAO4
Tractability: PROTAC: UniProt records ubiquitination sites on it; ubiquitination databases record sites on it; its protein half-life has been measured.
Gene: Protein-coding gene on chromosome 10 (97,458,083 to 97,499,500, reverse strand). Ensembl gene ENSG00000155229.
Subcellular location: Nucleus; Cytoplasm, cytoskeleton, spindle; Cytoplasm, cytoskeleton, microtubule organizing center, centrosome
Subcellular location (Human Protein Atlas): Nucleoplasm
Pathways (Reactome):
Metabolism: Cytosolic iron-sulfur cluster assembly
Gene Ontology:
Molecular function: nuclear estrogen receptor binding; protein binding; transcription coactivator activity; protein-macromolecule adaptor activity; signaling receptor complex adaptor activity; enzyme binding
Biological process: protein maturation; iron-sulfur cluster assembly; positive regulation of DNA-templated transcription
Cellular component: cytoplasm; cytosolic [4Fe-4S] assembly targeting complex; membrane; MMXD complex; nucleoplasm; nucleus; spindle; transcription factor TFIIH holo complex; centrosome
Genetic constraint (gnomAD): Loss-of-function variants: 70 observed, 108.47 expected, observed/expected ratio (o/e) 0.65, 90% interval 0.53 to 0.79. The upper end of that interval is the gene's LOEUF score, 0.79, which puts it in group 3 of 6, group 1 being the genes least tolerant of losing a copy. Missense variants: 1,124 observed, 1,172.3 expected, observed/expected ratio (o/e) 0.96, 90% interval 0.91 to 1.01. Synonymous variants: 478 observed, 466.63 expected, observed/expected ratio (o/e) 1.02, 90% interval 0.95 to 1.11.
Homologues: Orthologues: chimpanzee MMS19 (99% identical), macaque MMS19 (98% identical), dog MMS19 (93% identical), rabbit MMS19 (93% identical), pig MMS19 (92% identical), mouse Mms19 (90% identical), guinea pig MMS19 (90% identical), rat Mms19 (89% identical), tropical clawed frog mms19 (62% identical), zebrafish mms19 (55% identical), Drosophila melanogaster Mms19 (26% identical), Caenorhabditis elegans mms-19 (20% identical).
Diseases named in the same sentence as MMS19 in open-access papers:
MMS19 is named in the same sentence as 15 diseases in open-access papers, as found by Europe PMC text mining. Sharing a sentence is not in itself a finding about the gene and the disease. The quoted sentences say what the papers report.
breast carcinoma (3 papers, 2018 to 2025). "Enriched biological process and protein–protein interaction networks resulted in the identification of four novel breast cancer candidate genes namely MMS19, DNAH3, POLK and KATB6." (PMID 29879995, 2018). "In summary, these WES studies results and the functional annotation performed in the present study, altogether showed that MMS19, DNHA3, POLK and KATB6 are interesting breast cancer candidate genes." (PMID 29879995, 2018). "Only two genes (MMS19 and POLK) are involved in DNA repair pathway, considered as the traditional pathway in which breast cancer genes are involved." (PMID 29879995, 2018).
bladder carcinoma (1 paper, 2024). "It was shown in bladder carcinoma cells that overexpression of c-Myc and the resulting increase in MMS19 expression facilitate cell proliferation and the development of cisplatin resistance." (PMID 39409994, 2024).
esophageal cancer (1 paper, 2017). A primary or metastatic malignant neoplasm involving the esophagus. "Several genes/pathways have been implicated to esophageal cancer migration, such as Cdc42, HGF/SF, Androgen receptor, RhoA, Rac-1, and Cdc42, VEGF, HER2, PLCE1, ABCG2/V-ATPase, MMS19." (PMID 28147311, 2017).
head and neck squamous cell carcinoma (1 paper, 2021). A squamous cell carcinoma that arises from any of the following anatomic sites: lip and oral cavity, nasal cavity, paranasal sinuses, pharynx, larynx, and salivary glands. "Strikingly, the authors found that amplification of MAGE-F1, a component of the E3 ubiquitin ligase complex that regulates MMS19 degradation, was associated with significant increases in total mutation burden in lung and head and neck squamous cell carcinomas." (PMID 34857765, 2021).
osteosarcoma (1 paper, 2013). A usually aggressive malignant bone-forming mesenchymal neoplasm, predominantly affecting adolescents and young adults. "15,16 Our study has showed polymorphism in MMS19 is associated with good response of cisplatin chemotherapy in osteosarcoma, and our study provides evidence for further study to clarify their association." (PMID 24353725, 2013).
xeroderma pigmentosum (1 paper, 2019). Xeroderma pigmentosum (XP) is a rare genodermatosis characterized by extreme sensitivity to ultraviolet (UV)-induced changes in the skin and eyes, and multiple skin cancers. "Another interesting example pointing to an involvement of transcription factors in mitotic regulation is provided by studies on the human MMXD complex, which includes the MIP18, MMS19 and XPD proteins; XPD is also a component of TFIIH complex and is responsible for Xeroderma pigmentosum (XP)." (PMID 31527906, 2019).
cancer (6 papers, 2020 to 2025). A tumor composed of atypical neoplastic, often pleomorphic cells that invade other tissues. "Since disregulation of LTO1 and MMS19 contribute to tumorigenesis, we inspected the catalogue of somatic mutations in cancer and identified alterations in 6 human genes that would lead to decreased TCR functionality." (PMID 37883440, 2023). "Fe/S cluster assembly protein MMS19 was suggested to play a role in DNA repair, regulation of genome stability factors, and telomere maintenance, suggesting its importance in cancer biology." (PMID 37810966, 2023). "In fact, our analysis of TCGA data revealed that many cancers feature heterozygous deletion of MMS19 or CIA2B-FAM96B 43,44, and provides another compelling link between tumorigenesis and the fidelity of the CIA pathway." (PMID 34857765, 2021). "Intriguingly, the genes encoding MMS19 and CIA2B-FAM96B both reside in close proximity to tumor suppressor genes (PTEN and CDH1 respectively) that are frequently deleted in cancer, which increases susceptibility to passenger deletion." (PMID 34857765, 2021). "We also demonstrated that loss of either MMS19 or CIA2B-FAM96B is sufficient to alter the homeostasis of nucleotides and derivative metabolites in cancer cells, which likely contributes to the observed decrease in replication stress tolerance." (PMID 34857765, 2021). "Then, a CDM signature with five cancer-dependent genes (MMS19, NOP14, POLRMT, SNAPC5 and TIGD1) and a prognostic nomogram were constructed, and they demonstrated robust predictive performance and a close relationship with clinical characteristics in different CC datasets." (PMID 37441804, 2023). "Members of the cytosolic Fe/S assembly pathway- MMS19 and CIAO2B were found to be essential for replication stress tolerance of cancer cells towards Chk1 and ATR inhibition." (PMID 37810966, 2023).
tumor (2 papers, 2021 to 2023). "Methyl-methanesulfonate sensitivity 19 (MMS19) has been found in a variety of tumours and is involved in DNA metabolism and genomic stability through the regulation of nucleotide excision repair and Fe-S protein expression, thereby affecting tumor progression." (PMID 37441804, 2023).
neurodegenerative disease (1 paper, 2024). A disorder of the central nervous system characterized by gradual and progressive loss of neural tissue and neurologic function. "In particular, the recently reported implication of CTC genes ciao-1 and mms-19 in the onset of lethal neurodegenerative diseases highlights the significance of the work presented herein in assisting the study of human disease mechanisms." (PMID 39011897, 2024).
MMS19 also shares sentences with these, for which no sentence is quoted: adenocarcinoma (1 paper); familial breast cancer (1); head and neck cancer (1); non-small cell lung carcinoma (1); sarcoma (1); squamous cell carcinoma (1).